NRP2 (neuropilin 2)
Description:
High affinity receptor for semaphorins 3C, 3F, VEGF-165 and VEGF-145 isoforms of VEGF, and the PLGF-2 isoform of PGF. (Microbial infection) Acts as a receptor for human cytomegalovirus pentamer-dependent entry in epithelial and endothelial cells.
Synonyms: VEGF165R2; NP2; NPN2; PRO2714
Tractability: Antibody: UniProt places it where antibodies can reach, with high confidence; its Gene Ontology location is reachable by antibodies, with high confidence; UniProt predicts a signal peptide or a membrane-spanning region; the Human Protein Atlas places it where antibodies can reach. PROTAC: its protein half-life has been measured.
Gene: Protein-coding gene on chromosome 2 (205,681,990 to 205,798,133, forward strand). Ensembl gene ENSG00000118257.
Subcellular location: Membrane; Secreted (Isoform s9)
Subcellular location (Human Protein Atlas): Plasma membrane; Vesicles; Nucleoplasm; Predicted to be secreted
Pathways (Reactome):
Developmental Biology: NrCAM interactions
Signal Transduction: Neuropilin interactions with VEGF and VEGFR
Gene Ontology:
Molecular function: protein binding; cytokine binding; growth factor binding; semaphorin receptor activity; signaling receptor activity; vascular endothelial growth factor receptor activity
Biological process: angiogenesis; axon extension involved in axon guidance; axon guidance; branchiomotor neuron axon guidance; cell adhesion; facial nerve structural organization; nerve development; outflow tract septum morphogenesis; positive regulation of endothelial cell migration; positive regulation of endothelial cell proliferation; semaphorin-plexin signaling pathway; sympathetic ganglion development; sympathetic neuron projection extension; sympathetic neuron projection guidance; trigeminal nerve structural organization; dorsal root ganglion morphogenesis; facioacoustic ganglion development; gonadotrophin-releasing hormone neuronal migration to the hypothalamus; neural crest cell migration involved in autonomic nervous system development; neuron migration; regulation of postsynapse organization; sensory neuron axon guidance; trigeminal ganglion development; vascular endothelial growth factor signaling pathway; ventral trunk neural crest cell migration; and 1 more
Cellular component: extracellular region; axon; glutamatergic synapse; membrane; plasma membrane; postsynaptic membrane; semaphorin receptor complex
Genetic constraint (gnomAD): Loss-of-function variants: 47 observed, 106.68 expected, observed/expected ratio (o/e) 0.44, 90% interval 0.35 to 0.56. The upper end of that interval is the gene's LOEUF score, 0.56, which puts it in group 2 of 6, group 1 being the genes least tolerant of losing a copy. Missense variants: 1,002 observed, 1,217 expected, observed/expected ratio (o/e) 0.82, 90% interval 0.78 to 0.87. Synonymous variants: 489 observed, 482.2 expected, observed/expected ratio (o/e) 1.01, 90% interval 0.94 to 1.09.
Homologues: Orthologues: chimpanzee NRP2 (99% identical), macaque NRP2 (99% identical), rabbit NRP2 (96% identical), dog NRP2 (95% identical), mouse Nrp2 (95% identical), pig NRP2 (94% identical), rat Nrp2 (94% identical), guinea pig NRP2 (93% identical), tropical clawed frog nrp2 (70% identical), zebrafish nrp2b (59% identical), zebrafish nrp2a (57% identical). Paralogues in human: NRP1 (45% identical), CUBN (15% identical), CNTNAP5 (15% identical), CNTNAP4 (15% identical), CNTNAP2 (14% identical), CNTNAP3B (13% identical), CNTNAP3 (13% identical), F5 (13% identical), NRXN2 (13% identical), CNTNAP1 (12% identical), HEPH (12% identical), F8 (12% identical), and 23 more.
Diseases named in the same sentence as NRP2 in open-access papers:
NRP2 is named in the same sentence as 174 diseases in open-access papers, as found by Europe PMC text mining. Sharing a sentence is not in itself a finding about the gene and the disease. The quoted sentences say what the papers report.
breast carcinoma (49 papers, 2007 to 2025). "In mammary tumors, when recruited to hypoxic regions, tumor-associated macrophages with a high expression of NRP2, showed increased levels of MMP9, Tie-2, VEGF-A and HIF-1α." (PMID 38761292, 2024). "Increased NRP2 expression tends to be associated with lymph node metastasis and poor prognoses in breast cancer patients." (PMID 33396906, 2020). "More specifically, we show that NRP2 has a causal role in the ability of breast cancer cells to form mammospheres in vitro and initiate tumours in vivo." (PMID 23436775, 2013). "Finally, we showed that NRP2 expression levels are associated with the survival rates of breast cancer patients." (PMID 33396906, 2020). "Finally, high-NRP2 is shown to be associated with poor outcomes in breast cancer patients." (PMID 33396906, 2020). "The TGF-β/ miR-196a-3p/ NRP2 axis could provide further insight into the pathogenesis of breast cancer, and miR-196a-3p might be a potential diagnostic and therapeutic target for the metastasis of breast cancer." (PMID 28418877, 2017). "further showed that TAMs with high NRP2 expression, isolated from 4T1-derived murine breast cancer models, co-expressed both CD86 and CD206, whereas TAMs with low NRP2 expression were predominantly associated with high CD86 expression only." (PMID 40134439, 2025). "Our group has recently shown that Nrp2 is positively correlated with macrophage infiltration within paired primary and metastatic tumors from patients with breast cancer." (PMID 38592275, 2024). "One of these genes was NRP2, which is correlated with an unfavorable prognosis in breast cancer, especially in TNBC patients that receive radiotherapy." (PMID 39352757, 2024). "Breast cancer patients that had been given radiotherapy were selected from The Cancer Genome Atlas (TCGA) and separated based on their expression of NRP2 and NOS2 mRNA." (PMID 39352757, 2024). "Antibody-mediated disruption of Nrp2/VEGF-C has been found to reduce tumor lymphangiogenesis of murine mammary carcinoma and glioblastoma cell lines and was thought to inhibit metastasis by delaying the departure of tumor cells from the primary tumor." (PMID 38592275, 2024). "In oral squamous cell carcinoma and breast cancer, NRP2 was shown to positively influence the Wnt/β-catenin pathway." (PMID 38761292, 2024). "NRP-2 expression has been found in colon cancers, pancreatic cancers, breast cancers, osteosarcomas, melanoma, lung cancers, brain tumors, myeloid leukemia, infantile hemangioma, salivary adenoid cystic carcinoma, and ovarian neoplasms." (PMID 35052853, 2022). "Using murine cell lines and mammary tumor models along with analysis of human primary and metastatic breast cancers, we provide the first evidence of isoform-specific NRP2 expression and its consequences for macrophage function." (PMID 35651620, 2022). "Genetic depletion of either NRP2 isoform in macrophages resulted in a dramatic reduction of LPS-induced IL-10 production, defects in phagosomal processing of apoptotic breast cancer cells, and increase in cancer cell migration following co-culture." (PMID 35651620, 2022). "In a similar manner, we assessed the impact of codepleting endothelial NRP1 and NRP2 on a luminal B model of breast cancer." (PMID 36970722, 2022). "NRP2 isoforms were strongly correlated with the presence of macrophages in both primary and metastatic human breast cancer with levels up- or downregulated within ovarian and brain metastases, respectively." (PMID 35651620, 2022). "We define distinct phenotypes of NRP2 isoform-expressing TAMs in mouse models of breast cancer and within malignant pleural effusions from breast cancer patients which were exclusive of neuropilin-1 expression." (PMID 35651620, 2022). "NRP2 is undetectable in monocytes but is expressed on tissue-resident macrophages as well as TAMs within mouse mammary tumors and lung cancer patients." (PMID 35651620, 2022).
breast carcinoma (continued). "TAM subsets with high NRP1 co-expressed increased levels of CSF1R and decreased Ly-6C, indicating that NRP1 and NRP2 likely demark unique TAM subsets within murine mammary tumors." (PMID 35651620, 2022). "In order to determine if the NRP2 isoforms are differentially expressed in TAMs versus macrophages from normal mammary tissue, we examined healthy mammary glands and mammary tumors generated with the E0771 and 4T1 cell lines in mice." (PMID 35651620, 2022). "We observed a significant association between macrophages and both NRP2a and NRP2b in human primary and metastatic mammary tumors, with levels of the NRP2 isoforms varying dramatically between metastatic sites." (PMID 35651620, 2022). "Using transcriptional profiling and spectral flow cytometry, we show that NRP2 isoform expression was significantly higher in TAMs from murine mammary tumors." (PMID 35651620, 2022). "For example, NRP2 interacts with and functions as a co-receptor for the α6β1 integrin in breast cancer cells, which facilitates α6β1 signaling and activates focal adhesion kinase (FAK)." (PMID 34336654, 2021). "In breast cancer cells, neutralizing NRP2 antibody blocked cytoplasmic C-X-C Motif Chemokine Receptor 4 (CXCR4) expression which was followed by decreased tumor cell migration." (PMID 34239847, 2021). "To further clarify the role of NRP2 in breast cancer survival, we evaluated the breast cancer case data from The Cancer Genome Atlas (TCGA)." (PMID 33396906, 2020). "Given that the oncogenic functions of NRP2 activate many signaling pathways by binding with SEMA3C, we investigated the role of miR-146a (a regulator of NRP2 expression) in breast cancer aggressiveness." (PMID 33396906, 2020). "Activation of NRP2 is necessary for transforming growth factor-β1-induced migration and invasion of breast cancer cells." (PMID 32373927, 2020). "TGFβ1-mediated inhibition of miR-196a-3p and consequent activation of NRP2 promotes a metastatic phenotype of breast cancer cells." (PMID 30717262, 2019). "For example, NRP2 can interact with and function as a co-receptor for the α6β1 integrin in breast cancer cells." (PMID 30678134, 2019). "In breast cancer, for example, NRP2 is expressed preferentially in TNBCs compared to other breast cancer sub-types and it is enriched in breast CSCs." (PMID 30678134, 2019). "Another breast cancer study highlighted the role of VEGF-C/NRP2 signaling in enhancing CSC characteristics." (PMID 30678134, 2019). "In breast carcinoma cells, NRP2/VEGF signaling increases FAK indirectly by activation of integrin α6β1." (PMID 30717262, 2019). "GLI1 in turn induces expression of BMI-1, a key stem cell factor, in breast cancer and enhances expression of integrin α6β1 and NRP2 in an autocrine loop." (PMID 30717262, 2019). "In a similar way, NRP2-mediated VEGF signaling in breast cancer and prostate carcinoma cells is subject to modulation by integrin α6β1." (PMID 30717262, 2019). "The effects of the NRP2 siRNA on the viability of breast cancer cells was examined using the MTT assay, which showed that NRP2 silencing did not change the proliferative properties of the cells, consistent with effect of the miR-196a-3p mimic." (PMID 28418877, 2017). "In summary, we showed that miR-196a-3p is stimulated by TGF-β1 and contributes to cell metastasis by targeting NRP2 in breast cancer." (PMID 28418877, 2017). "The data showed that upregulation of NRP2 significantly correlated in human lung cancer and breast cancer specimens." (PMID 28796261, 2017). "Neuropilin 2 (NRP2) can modulate lymphangiogenesis, but its relationship with the metastasis of breast cancer is unclear." (PMID 28356139, 2017). "Based on the mRNA and protein expression of the two candidate target genes in response to miR-196a-3p mimics, we focused on NRP2 as a target gene of miR-196a-3p in breast cancer." (PMID 28418877, 2017).
breast carcinoma (continued). "We also identified the protein neuropilin 2 (NRP2) as a downstream target of miR-196a-3p, and showed that blocking NRP2 expression potently antagonized TGF-β promigratory effects in invasive breast cancer cells." (PMID 28418877, 2017). "We, therefore, provoked breast cancer cell invasiveness by knocking down Rab17 or Vamp8 and tested the requirement for NRP2 in this." (PMID 28062852, 2017). "Here, we proposed a model in which TGF-β is capable of inducing tumorigenic through the reduction of miR-196a-3p, which targets NRP2, leading to its accumulation, providing novel potential targets for the treatment of metastatic breast cancers." (PMID 28418877, 2017). "Applying the Gene Set Analysis (GSA) we found that elevated expression of HRH1, EFNB1, KLK1, NRP2, and APP was associated with the basal-like subtypes of breast cancer as predicted by the MicMa cohort." (PMID 26673618, 2016). "Although other authors have already reported that HRH1 and NRP2 were involved in breast cancer development and progression, to our knowledge, the overexpression of these genes had not been correlated with basal-related breast cancer subtypes." (PMID 26673618, 2016). "NRP2 expression is correlated with lymph node metastasis in breast cancer and blocking of NRP2 leads to decreased metastasis formation." (PMID 26573807, 2015). "This phenotype is consistent with the observation that NRP2 expression in human breast cancer correlates with aggressive disease and poor clinical outcome." (PMID 23436775, 2013). "More definitive data to evaluate the role of GLI1 in tumour initiation and its relationship to NRP2 were obtained using a transgenic mouse model of breast cancer in which GLI1 is expressed under the regulation of the MMTV promoter." (PMID 23436775, 2013). "Intriguingly C100, a breast cancer cell line that expresses both Nrp1 and Nrp2, responds to exogenous Sema3f with inhibition of cell spreading, and this response is insensitive to the addition of anti-Nrp1 functional blocking antibody." (PMID 22783168, 2012). "It should be noted that others have reported a much higher frequency of Nrp2 expression (~ 50%) by tumor cells in breast cancer." (PMID 22948112, 2012). "In breast cancers, NRP2 expression is significantly correlated with lymph node metastasis, VEGF-C expression and cytoplasmic CXCR4 expression." (PMID 24212788, 2011). "NRP2 expression was shown to promote the malignant phenotype of colon cancers, pancreatic cancers, and breast cancers." (PMID 21747928, 2011). "NRP2 was expressed on 3 out of 10 colon carcinoma, 5 out of 15 breast carcinoma and 4 out of 12 pancreatic carcinoma." (PMID 21747928, 2011). "The present study, to our knowledge, is the first one to demonstrate the clinicopathological significance of Nrp2 expression in human breast cancer." (PMID 19580679, 2009). "Recently, Nrp2 was shown to play a role in cancer by promoting migration of breast cancer cells, which correlates with tumor cell metastasis." (PMID 19580679, 2009). "Here we demonstrate the presence of NRP2a and NRP2b in macrophages, the co-enrichment of both isoforms in TAMs within murine and human breast cancer and speculate that NRP2 and NRP1 denote unique TAM subsets." (PMID 35651620, 2022). "As observed in mouse mammary tumors, macrophage subsets which expressed high levels of NRP2Total and NRP2b did not express significant NRP1, suggesting that NRP1 and NRP2 are associated with discrete macrophage populations in human breast cancer MPEs." (PMID 35651620, 2022). "However, VEGFC levels are very low in three out of five breast cancer cell lines and NRP2 levels are very low in all the breast cell lines including MDAMB231." (PMID 33461580, 2021). "Overall, these findings suggest that regulation of NRP2 expression may be a key therapeutic option in breast cancer." (PMID 33396906, 2020). "In summary, many studies have indicated that NRP2 and miR-146a may prevent the deterioration of breast cancer." (PMID 33396906, 2020).
breast carcinoma (continued). "A truncated and thus noncyclic tumor-homing peptide tPlP-1 shows a promising possibility for targeting therapeutic and diagnostic agents to breast cancer cells, as it binds to both NRP1 and NRP2 and improves extravasation of co-injected nanoparticles into the tumor tissue." (PMID 30717262, 2019). "In addition, the level of NRP2 expression was negatively related to the expression of miR-196a-3p in breast cancers, especially in TNBC." (PMID 28418877, 2017). "Thus, immunoprecipitation analysis revealed that NRP2 interacts with α5 integrin in endothelial cells and with α6β1 integrin in melanoma and breast cancer cells." (PMID 26923176, 2016). "Importantly, knockdown of Nrp2 sensitized 66 cl4 mammary carcinoma cells to oxidative stress-induced cell death, similar to what we observed with VEGF-C KD." (PMID 25358638, 2014). "Indeed, knockdown of Nrp2 in the 66 cl4 mammary carcinoma cell line led to a significant decrease in Sod3 expression compared to control KD cells." (PMID 25358638, 2014). "The frequency of tumors with Nrp2+ tumor cells was comparable to Nrp1 in breast cancer and NSCLC." (PMID 22948112, 2012). "Nrp2 expression may serve as a significant prognostic factor for long-term survival in breast cancer." (PMID 19580679, 2009). "Notably, Nrp2 high macrophages lacked Nrp1 expression, suggesting that Nrp2 and Nrp1 are associated with discrete macrophage populations in breast cancer MPEs." (PMID 38592275, 2024). "NRP2 may also be a marker of poor prognosis in breast cancer." (PMID 35564499, 2022). "Collectively, our studies illustrate the dynamic nature of NRP2 isoform expression in breast cancer and suggest that targeting NPR2 isoform-specific signaling pathways or NRP2-isoform expressing TAM subsets may be leveraged for macrophage reprograming or TAM-targeted immunotherapies." (PMID 35651620, 2022). "In addition, HRH1 and NRP2 should be considered interesting targets for the treatment of basal-related breast cancer subtypes, and STX1A could be an interesting target for the treatment of the luminal B and HER2-enriched subtypes." (PMID 26673618, 2016). "Therefore, we hypothesize that NRP2 expression might promote tumor angiogenesis and metastasis in basal-like breast cancer." (PMID 26673618, 2016). "Therefore, therapies targeting HRH1, STX1A, and NRP2 might improve outcomes in basal-related breast cancer." (PMID 26673618, 2016). "Furthermore, NRP2 plays a role in breast cancer metastasis by promoting migration and invasion." (PMID 26673618, 2016). "Indeed, Nrp1 or Nrp2 expression is significantly associated with poor survival in breast cancer, independent of other standard prognostic factors." (PMID 22948112, 2012). "Indeed, NRP2 expression was found in osteosarcoma, melanoma, lung cancers, brain tumors colon cancers, pancreatic cancers, breast cancers, myeloid leukemia, salivary adenoid cystic carcinoma, infantile hemangioma, ovarian neoplasms and bladder cancers." (PMID 21747928, 2011). "The VEGF-C/NRP2/GLI axis is a novel and conserved paracrine means by which EMT cells promote proliferation, migration, and invasion of epithelial breast cancer cells." (PMID 38498906, 2024). "We revealed SEMA3F as a promoter of invasion during the DCIS-to-invasive ductal carcinoma transition in breast cancer (BC) through the action of NRP1 and NRP2." (PMID 39138514, 2024). "By contrast, SEMA3F and its receptor, NRP-2, have roles in cell migration; for example, SEMA3F gradients had repulsive effects on the migration of thymocytes and the highly motile C100 breast cancer cells —an effect that was blocked by an anti-NRP-2 antibody." (PMID 37685898, 2023). "Lastly, we found that NRP1, NRP2, PLXNA1, C1, and D1 had the highest correlation with the expression of immune checkpoint molecules PD1/PDL1 and CTLA-4 in breast cancer." (PMID 32640719, 2020).